APOE (apolipoprotein E)
Diseases named in the same sentence as APOE in open-access papers (continued):
Sharing a sentence is not in itself a finding about the gene and the disease.
substance abuse (2 papers, 2015 to 2025). The use of a drug for a reason other than which it was intended or in a manner or in quantities other than directed. "The demographics, including the primary source of mTBI (mild Traumatic Brain Injury), age and cause of death, ApoE genotype, and history of substance abuse, when listed, were obtained from each case report." (PMID 25671598, 2015). "According to this speculative hypothesis, genetic predisposition (APOE4 [Apolipoprotein E4]), aging, stress, and substance abuse can induce dysbiosis of microbial flora of the gut." (PMID 41002922, 2025).
Thiamine deficiency (2 papers, 2018 to 2023). Thiamine deficiency is a condition that occurs due to not enough thiamine (vitamin B1).
thyroid tumor (2 papers, 2022 to 2025). A benign or malignant neoplasm affecting the thyroid gland. "The observed discrepancies in CD99 and CD6 binding in APOE‐low thyroid tumour cells contribute to oncogenic functions, although the underlying mechanisms require further investigation." (PMID 39810624, 2025). "With the advantage of an integrated spatial transcriptome, we also discovered that thyroid tumour cells with low APOE expression interacted with DCs and CD4+ T cells via CD99‐regulated signalling but minimally interacted with the CD6 receptor." (PMID 39810624, 2025). "Our data further indicated that thyroid tumour cells with low APOE expression exhibited significantly decreased overall intercellular communication with immune cells, particularly NK and T cells." (PMID 39810624, 2025). "Immunohistochemical indicated that APOE stained highly in thyroid tumor, while HTRA3 and MT1A showed the reverse staining results." (PMID 36387901, 2022). "The protein levels of HTRA3 and MT1A were significantly attenuated, but APOE protein level was increased in thyroid tumor." (PMID 36387901, 2022).
triple-negative breast carcinoma (2 papers, 2025). An invasive breast carcinoma which is negative for expression of estrogen receptor (ER), progesterone receptor (PR), and human epidermal growth factor receptor 2 (HER2). "Similarly, Macro_APOE impaired immunotherapy efficacy via interactions with CD8Tex in triple-negative breast cancer, an effect reversible through APOE blockade." (PMID 40963562, 2025).
ulcers (2 papers, 2023 to 2024). "The Kruskal–Wallis test statistic of 13.18 and a highly significant p-value of 0.0014 suggest that APOE plays an essential role in the progression of DFUs, particularly in relation to non-healing ulcers." (PMID 39409014, 2024). "This, accompanied by the high abundance of amyloid-beta precursor protein (APP), apolipoprotein E (APOE), MADD (MAP kinase-activating death domain protein), ATF6B, ERN1 and TRAP1 in the presence of ulcers, shows that, along with cell death, the epithelial health maintenance response is strong." (PMID 37170213, 2023).
uveitis (2 papers, 2020 to 2022). An inflammatory process affecting a part of or the entire uvea. "They found the total protein concentration to be increased in the inflamed aqueous of both uveitis models, as compared to the naïve aqueous, including calprotectin (a heterodimer of S100A8 and S100A9) and apolipoprotein E. Apolipoprotein E had higher levels in EAU than PMU in the aqueous." (PMID 33343583, 2020).
abetalipoproteinemia (1 paper, 2025). "Additionally, elevated plasma concentrations of ApoE in the HDL fraction are observed in patients with abetalipoproteinemia, suggesting that ApoE may play a significant role in lipid secretion in place of ApoB under certain pathological conditions." (PMID 40180213, 2025).
acute monocytic leukemia (1 paper, 2011). Acute monoblastic leukemia (AML-M5), is one of the most common subtypes of acute myeloid leukemia (AML) that is either comprised of more than 80% of monoblasts (AML-M5a) or 30-80% monoblasts with (pro)monocytic differentiation (AML-M5b). "IFN-γ dramatically increased the degradation of intracellular apoE and inhibited the accumulation of apoE in the supernatants of human monocyte-derived macrophages and human acute monocytic leukemia cell line (THP-1) cells via post-translational modification of apoE." (PMID 21772670, 2011).
Adrenal insufficiency (1 paper, 2014). Insufficient production of steroid hormones (primarily cortisol) by the adrenal glands. "Because sea lion samples included in the adrenal insufficiency study were also included in this study, it is possible, but speculative, that DAT through the axis of ApoE could lead to metabolic disturbances in cholesterol metabolism in the adrenal gland." (PMID 25919366, 2014).
Agitation (1 paper, 2023). A state of excessive motor activity that is associated with mental distress or a feeling of substantial unease or inner tension. "Here, we report the generation of human-induced pluripotent stem cells (iPSCs) from a 74-year-old AD patient, the homozygous APOE ε4/ε4 carrier, who developed Agitation." (PMID 38137534, 2023).
aspergillosis (1 paper, 2020). Aspergillosis is an infection, growth, or allergic response caused by the Aspergillus fungus. "Interestingly, in our study protein levels for ApoB were significantly decreased in both hosts during aspergillosis; additionally, elevated levels for apolipoprotein E and N were detected in mice." (PMID 33043780, 2020).
aspiration pneumonia (1 paper, 2022). "One of the unexpected findings was that APOE was the SNP associated with aspiration pneumonia, which contradicts previous findings that reported that the major allele of rs4252961 in IL1RN was associated with infection risk." (PMID 36005151, 2022). "The comparison of baseline parameters according to APOE genotype in the young age group showed that those with APOE ɛ4 had more aspiration pneumonia and had poorer initial PAS scores." (PMID 36005151, 2022). "In contrast, no APOE allele seemed to play a role in increasing the risk of aspiration pneumonia in the elderly group." (PMID 36005151, 2022). "In fact, 44.6% of the young and 61.2% of the elderly patients had aspiration pneumonia history, with more aspiration pneumonia in the elderly group, regardless of APOE ɛ4 presence." (PMID 36005151, 2022). "The two participants with APOE ɛ2/ɛ4 did not experience aspiration pneumonia." (PMID 36005151, 2022).
asthenozoospermia (1 paper, 2023). "In detail, the combination of the three proteins APCS, APOE, and FLOT1 predicts male subfertility in general, the two combined proteins APOE and FN1 predicts asthenozoospermia, and the two combined proteins RUVBL1 and TFKC oligoasthenozoospermia." (PMID 37048090, 2023).
Azoospermia (1 paper, 2024). Absence of any measurable level of sperm,whereby spermatozoa cannot be observed even after centrifugation of the semen pellet. "While we did not observe changes in TNF expression in the blood of individuals with CAIS, it does not preclude the involvement of apolipoprotein E (APOE)-relevant mechanisms in azoospermia and other DSD-relevant phenotypes, as it was reported in microglia." (PMID 38212646, 2024).
babesiosis (1 paper, 2023). Babesiosis refers to a condition caused by microscopic parasites that infect the red blood cells. "Higher abundances of apoE were found in complicated compared to uncomplicated babesiosis, as well as in uncomplicated compared to control group, and in complicated babesiosis compared to controls, as confirmed by western blotting." (PMID 37353646, 2023). "Other identified proteins that differentiated uncomplicated from complicated babesiosis were various complement cascade components (CFI, CFP, C2, SERPING1, C8G), extracellular matrix components (TGFBI), acute phase proteins (ORM1, ITIH2, ITIH4, FGA, TF, RBP4) and lipoproteins (apoE)." (PMID 37353646, 2023).
bacteremia (1 paper, 2023). "pneumoniae, we then sought to optimize the infecting dose in Western diet fed ApoE-/- mice to maximize the percentage of mice with bacteremia." (PMID 37033482, 2023). "This is reflected in the fact that deaths were seen even in ApoE-/- mice without bacteremia 24 hours post infection." (PMID 37033482, 2023).
bacterial meningitis (1 paper, 2022). Inflammation of the membranes surrounding the brain and spinal cord due to a bacterial infection. "Unlike our findings, the CSF levels of ApoE increased in bacterial meningitis in pediatric patients aged from 2 months to 13 years." (PMID 35634471, 2022).
biliary tract cancer (1 paper, 2025). "Interestingly, the variants in HFE, APOE, and TERT displayed concordant effects on HCC and biliary tract cancer." (PMID 40823170, 2025). "APOE, which affects both HCC and biliary tract cancer, was primarily expressed in hepatocytes." (PMID 40823170, 2025).
bronchiectasis (1 paper, 2021). Segmental, irreversible dilation of the bronchial tree resulting in the accumulation of secretions which leads to obstruction. "During this process, PD-fed ApoE KO rats developed severe bronchiectasis in a short period (Figure 6H1)." (PMID 34361033, 2021).
bronchopulmonary dysplasia (1 paper, 2022). Bronchopulmonary dysplasia is a chronic respiratory disease that results from complications related to lung injury during the treatment of infant acute respiratory distress syndrome in low-birth-weight premature infants or from abnormal lung development in older infants. "Multi-omics studies have revealed the biological characteristics of APOE transgenic mice, bronchopulmonary dysplasia, and plant tolerant to heavy metals." (PMID 36523490, 2022).
Cachexia (1 paper, 2019). Severe weight loss, wasting of muscle, loss of appetite, and general debility related to a chronic disease. "In contrast, BMI, plasma concentrations of hemoglobin, lymphocyte count, total protein, albumin, prealbumin, total cholesterol and ApoE of patients in the cancer cachexia group were significantly lower than in non-cachexia group." (PMID 31788012, 2019). "Direct comparisons were made between male and female cancer cachexia patients, which revealed significant differences in FFA and ApoE in opposite genders." (PMID 31788012, 2019). "Similarly, when comparisons were made between female cancer cachexia and female non-cachexia patients, IL-6 and FFA were remarkably higher in the cachexia group, while BMI, total cholesterol, ApoE and prealbumin were apparently lower in the cachexia group." (PMID 31788012, 2019). "When male cancer cachexia and male non-cachexia patients were compared, IL-6 and platelet were significantly elevated in the cachexia group, whereas total protein, albumin, prealbumin, ApoE, lymphocyte counts and hemoglobin were significantly reduced in the cachexia group." (PMID 31788012, 2019).
candidiasis (1 paper, 2024). Infection with the organism Candida. "The role of lipid dysmetabolism in susceptibility to candidiasis is evidenced both in vitro and in the ApoE deficient mouse model." (PMID 38455763, 2024). "In the ApoE deficient mouse model, wherein there is depleted lipoproteins and increased VLDL, these mice exhibit increased susceptibility to candidiasis." (PMID 38455763, 2024).
cervical spondylosis (1 paper, 2020). "In the APOE gene, the ε4 allele was found to be associated with an increased risk of myelopathy in a case-control study, where the controls had cervical spondylosis without myelopathy (OR 3.50, p = 0.008)." (PMID 31968564, 2020).
cervical squamous cell carcinoma (1 paper, 2021). A squamous cell carcinoma arising from the cervical epithelium. "Additionally, studies have shown that concentrations of APOA1, APOE, and CLU were differentially expressed in cervical squamous cell carcinoma patients when compared to those with benign lesions and were associated with the histological classification or the processing of the cervical lesion." (PMID 33521130, 2021).
cholesterol metabolism disorder (1 paper, 2023). "Subsequently, it was proven by gene set enrichment analysis and qPCR, that ApoE played a key role in developing cholesterol metabolism disorder in S. aureus osteomyelitis." (PMID 37529351, 2023).
chronic inflammatory demyelinating polyneuropathy (1 paper, 2012). "For example, APOE (apolipoproteinE), a lipid metabolism-related protein, has been shown to protect mice from chronic inflammatory demyelinating polyneuropathy by affecting the antigen-presenting function of SCs, and to benefit axonal reconstruction and myelin membranes." (PMID 22443529, 2012).
chronic lymphocytic leukemia (1 paper, 2019). "Some of the genes detected in our study include the apolipoprotein gene cluster (APOC1, APOC2, APOE), which are shown to have tight linkage with a chronic lymphocytic leukemia-associated translocation breakpoint." (PMID 31013791, 2019).
chronic venous insufficiency disease (1 paper, 2024). "This research aimed to investigate the presence of APOE gene variants in individuals with chronic venous insufficiency disease and validate the relationship between this gene and cardiovascular diseases." (PMID 38540308, 2024).
coagulopathy (1 paper, 2019). "Both TAT and PT values in Alox−/− single or double knockouts showed far higher variability than either wild-type or ApoE−/− mice, indicating that the extent of Alox−/−-associated coagulopathy varies between individual mice." (PMID 30944221, 2019).
cystic kidney disease (1 paper, 2025). A congenital or acquired kidney disorder characterized by the presence of renal cysts. "Seven genes (3%) had no entries in OMIM (DLG5 in renal ciliopathies and cystic kidney diseases; and 6 in the proteinuric kidney diseases [APOE, DLC1, FAT1, ITSN1, PODXL and TNS2]) and were excluded." (PMID 40303230, 2025).
degenerative disc disorders (1 paper, 2019). "APOE-knockout rabbits can be used as a new model to set up a stable, less immunogenic and non-pathogenic ex vivo gene therapy system to enhance the regeneration potential of NP cells and advance the treatment strategies of degenerative disc disorders." (PMID 31751427, 2019). "APOE-knockout rabbits would be used as a favourable in vivo model for rational therapeutic approaches of degenerative disc disorders." (PMID 31751427, 2019). "Therefore, APOE-knockout rabbits could be used as a promising animal model for therapeutic approaches of degenerative disc disorders." (PMID 31751427, 2019). "Thus, APOE-knockout rabbits could be used as a promising model for therapeutic approaches of degenerative disc disorders." (PMID 31751427, 2019).
Dysferlinopathies (1 paper, 2024). "Cholesterol is highly enriched in the T-tubule of myofibers and appears to be the key culprit behind disease exacerbation caused by ApoE inactivation in both DMD and Dysferlinopathies as cholesterol absorption blocker ezetimibe drastically reduces disease severity." (PMID 39716324, 2024).
Dystonia (1 paper, 2020). An abnormally increased muscular tone that causes fixed abnormal postures. "Furthermore, some variants in brain-derived neurotrophic factor (BDNF) and apolipoprotein E (APOE) have also been reported to lead to an increased incidence of dystonia, possibly via altered neural plasticity." (PMID 32670041, 2020).
energy metabolism disorders (1 paper, 2025). "The downregulation of subtype-specific candidate markers ACO2 and APOE correlates with energy metabolism disorders (tricarboxylic acid cycle) and lipid homeostasis imbalance associated with moderate-to-severe SSNHL, respectively." (PMID 41312345, 2025).
enteritis (1 paper, 2025). Inflammation of the small intestine. "We explored the role of the APOE gene using apoE-deficient mice challenged by C. difficile toxin A (TcdA)-induced enteritis, and the potential use of the ApoE mimetic peptide in repairing the intestinal damage induced by TcdA." (PMID 41416135, 2025).
Fabry disease (1 paper, 2021). Fabry disease (FD) is a progressive, inherited, multisystemic lysosomal storage disease characterized by specific neurological, cutaneous, renal, cardiovascular, cochleo-vestibular and cerebrovascular manifestations. "We genetically diagnosed the rare diseases including lipoprotein nephropathy with APOE variant (AD, 2), nephronophthisis (NPHP, AR, 2), Fabry disease with GLA variant (XLR,1), renal coloboma syndrome (AD, 2), and mitochondrial disease." (PMID 34215756, 2021).
familial chylomicronemia syndrome (1 paper, 2017). A rare autosomal recessive disease characterized by the buildup in the blood of fat particles called chylomicrons (chylomicronemia), severe hypertriglyceridemia, and the risk of recurrent and potentially fatal pancreatitis and other complications. "Remarkably, this was associated with ∼50% decreases in both apoC-II and apoE, and modest increases in apoA-I, apoA-II, and apoM, whereas levels of apoB-100 did not change, except in the 3 subjects with familial chylomicronemia syndrome (FCS) (IONIS1), who experienced a marked decrease in TGs." (PMID 28209220, 2017).
Fanconi anemia (1 paper, 2015). Fanconi anemia (FA) is a hereditary DNA repair disorder characterized by progressive pancytopenia with bone marrow failure, variable congenital malformations and predisposition to develop hematological or solid tumors. "We performed DRIP-qPCR in four human genes, APOE, RPL13A, EGR1 and BTBD19 in well-established cell lines derived from Fanconi Anemia patients." (PMID 26584049, 2015).
focal segmental glomerulosclerosis (1 paper, 2014). A renal disorder characterized by sclerotic lesions in the glomeruli. "Increased glomerular APOE expression was observed in patients with idiopathic nephrotic syndrome but it is rather a rare occurrence in focal segmental glomerulosclerosis (FSGS)." (PMID 25352833, 2014).
gallbladder NET (1 paper, 2021). "The immunosuppressive TME in epithelial GC consist of infiltrating CD4+ T‐reg, CXCL13+ Th cells, CCL20lo/CD163hi, and APOE+ macrophages; however, it is the immune‐desert phenotype for gallbladder NET." (PMID 34185421, 2021).
generalised brain atrophy (1 paper, 2013). "Future studies should carefully consider: 1) their specific techniques in adjusting for brain size; 2) assessing more detailed sub-divisions of the hippocampal formation; and 3) testing whether significant APOE-hippocampal associations are independent of generalised brain atrophy." (PMID 24260406, 2013).
genital herpes (1 paper, 2022). Herpes simplex infection of the genitals, most commonly caused by the herpes simplex-2 virus. "In genital herpes, caused by HSV-2, APOE-ε4 is a risk for the recurrence of genital ulcers." (PMID 39483362, 2022).
Guillain-Barre syndrome (1 paper, 2010). A spectrum of rare post-infectious neuropathies that usually occur in otherwise healthy patients. "In several studies aiming at finding specific biomarkers in the cerebrospinal fluid (CSF) of human Guillain-Barré syndrome (GBS), an analog of MS in the peripheral nervous system, apoE was shown to decrease in CSF in GBS patients by proteomic analysis and ELISA." (PMID 20613949, 2010).
Helminth infection (1 paper, 2025). "Helminth infection also significantly lowered the lipid accumulation in liver, which may attribute to the significant up-regulated expression levels of apolipoprotein E (ApoE) and down-regulated expression of peroxisome proliferator-activated receptor-gamma (PPAR-γ) and lipoprotein lipase (LPL)." (PMID 40708918, 2025).
Hernia (1 paper, 2018). "Apolipoproteins were analyzed with an immunoassay for multiplexed detection of APOA1, APOA2, APOB, APOC2, APOC3, and APOE, and all six proteins were found to be significantly elevated in urine samples of BC patients when compared to controls (hernia patient volunteers)." (PMID 30544619, 2018).